TMEM154 (transmembrane protein 154)
Synonyms: FLJ32028
Tractability: Antibody: UniProt predicts a signal peptide or a membrane-spanning region.
Gene: Protein-coding gene on chromosome 4 (152,618,628 to 152,680,012, reverse strand). Ensembl gene ENSG00000170006.
Subcellular location: Membrane
Subcellular location (Human Protein Atlas): Nuclear membrane; Nucleoplasm
Gene Ontology:
Molecular function: protein binding
Cellular component: membrane
Genetic constraint (gnomAD): Loss-of-function variants: 24 observed, 22.44 expected, observed/expected ratio (o/e) 1.07, 90% interval 0.77 to 1.5. The upper end of that interval is the gene's LOEUF score, 1.5, which puts it in group 6 of 6, group 1 being the genes least tolerant of losing a copy. Missense variants: 222 observed, 214.04 expected, observed/expected ratio (o/e) 1.04, 90% interval 0.93 to 1.16. Synonymous variants: 65 observed, 80 expected, observed/expected ratio (o/e) 0.81, 90% interval 0.66 to 1.
Homologues: Orthologues: macaque TMEM154 (88% identical), pig TMEM154 (68% identical), dog TMEM154 (67% identical), rabbit TMEM154 (67% identical), mouse Tmem154 (65% identical), guinea pig TMEM154 (59% identical), rat Tmem154 (57% identical).
Diseases named in the same sentence as TMEM154 in open-access papers:
TMEM154 is named in the same sentence as 16 diseases in open-access papers, as found by Europe PMC text mining. Sharing a sentence is not in itself a finding about the gene and the disease. The quoted sentences say what the papers report.
type 2 diabetes (5 papers, 2014 to 2023). "Studies of type 2 diabetes intermediary traits suggest the diabetogenic impact of the C-allele of TMEM154-rs6813195 is mediated through reduced beta cell function." (PMID 25799151, 2015). "We confirmed associations with type 2 diabetes for five of the seven SNPs (TMEM154-rs6813195, FAF1-rs17106184, POU5F1/TCF19-rs3130501, ARL15-rs702634 and ABCB9/MPHOSPH9-rs4275659)." (PMID 25799151, 2015). "A trans-ethnic meta-analysis of type 2 diabetes genome-wide association studies has identified seven novel susceptibility variants in or near TMEM154, SSR1/RREB1, FAF1, POU5F1/TCF19, LPP, ARL15 and ABCB9/MPHOSPH9." (PMID 25799151, 2015). "SNP rs6813195 near to TMEM154 was nominally associated with type 2 diabetes (p = 0.01, OR 1.12 [95% CI 1.03, 1.22]) and adiposity: the type 2 diabetes risk allele was associated with a lower percentage body fat (β = −1.451%, p = 4.8 × 10−4)." (PMID 25112377, 2014). "We performed a replication study in a Japanese population to evaluate the association between type 2 diabetes and six susceptibility loci (TMEM154, SSR1, FAF1, POU5F1, ARL15, and MPHOSPH9) originally identified by a transethnic meta-analysis of genome-wide association studies (GWAS) in 2014." (PMID 27115357, 2016). "We confirm the role of ZFAND6, PRC1 and TMEM154 in the pathophysiology of type 2 diabetes among Indians." (PMID 37738238, 2023). "We examined the association of six SNP loci, rs6813195 near TMEM154, rs9505118 in SSR1, rs17106184 in FAF1, rs3130501 in POU5F1, rs702634 in ARL15, and rs4275659 near MPHOSPH9, identified by transethnic GWAS meta-analysis with susceptibility to type 2 diabetes in a Japanese population." (PMID 27115357, 2016).
scrapie (4 papers, 2013 to 2024). A fatal disease of the nervous system in sheep and goats, characterized by pruritus, debility, and locomotor incoordination. "Marker-assisted selection (MAS) offers another possibility to breed healthy animals, since it was found to use the polymorphism of the transmembrane protein 154 (TMEM154) gene as a marker for lentivirus-resistant sheep, followed by cases of scrapie in selective breeding." (PMID 27399757, 2016).
lentivirus infection (3 papers, 2012 to 2022). Virus diseases caused by the Lentivirus genus. "A single nucleotide polymorphism (rs408593969, c.103G>A, missense mutation E35K) in the ovine transmembrane protein gene 154 (TMEM154) was identified as protective against small ruminant lentivirus infection in different herds worldwide." (PMID 35906709, 2022). "Ovine DNA sequence variation in a transmembrane protein gene (TMEM154) was associated with lentivirus infection." (PMID 22291605, 2012). "Together, these findings indicate that TMEM154 may play a central role in ovine lentivirus infection and removing sheep with the most susceptible genotypes may help eradicate OPP and protect flocks from reinfection." (PMID 22291605, 2012). "Thus, comparing the relative level of resistance conferred by various TMEM154 haplotypes, together with the identification of additional host genetic risk factors, will be important for developing flocks that are genetically resistant to lentivirus infections." (PMID 22291605, 2012). "These cohort studies also confirmed that TMEM154 haplotype alleles 2 and 3 are significant risk factors for OPPV infection in various breeds, and may be associated with lentivirus infection in multiple geographic locations and environments." (PMID 22291605, 2012). "Although the biological function of TMEM154 is unknown, our results indicate that it plays an important role in lentivirus infection in sheep." (PMID 22291605, 2012).
asthma (2 papers, 2012 to 2021). "A recent study identified TMEM154 in a human GWAS for asthma severity, suggesting that TMEM154 may play a conserved role in airway immune responses." (PMID 23082221, 2012).
latent infection (1 paper, 2022). "Although, we cannot exclude the possibility of the animal having a very low level latent infection below the detection limits of the assay, the study still adds more evidence to the body of data that homozygosity for K at TMEM154 E35K represents a genuine genetic resistance marker for MV." (PMID 35144720, 2022).
infection (22 papers, 2012 to 2025). The state of being infected such as from the introduction of a foreign agent such as serum, vaccine, antigenic substance or organism. "Two TMEM154 haplotypes (2 and 3, ancestral), carrying a nucleotide (G) encoding for glutamic acid (E) at position 35, were associated with infection, while haplotype 1 encodes a lysine (K) at position 35 and has been associated with resistance." (PMID 40844279, 2025). "Association between the genetic variation in the ovine transmembrane 154 (TMEM154) gene and susceptibility to certain viral subtypes was previously demonstrated, representing a possible control strategy to reduce infection prevalence in sheep." (PMID 40844279, 2025). "TMEM154 is associated with lentivirus susceptibility, and selecting resistant genotypes can help prevent infection." (PMID 41012812, 2025). "The odds of infection for RPL sheep carrying one or two copies of TMEM154 allele E at codon 35 were 2.5 times higher than those for sheep homozygous for the K allele (p = 0.09, OR = 2.487, CI 95% = 0.847–7.303)." (PMID 41394915, 2025). "An association between the genetic variation in the ovine transmembrane 154 (TMEM154) protein coding gene and infection susceptibility to certain SRLV subtypes was demonstrated with a genome-wide association study (GWAS) approach." (PMID 40844279, 2025). "This study aimed to investigate the presence of single polymorphic sites in TMEM154 gene in sheep of selected Polish flocks and assess their association with the infection and proviral load in the context of susceptibility to SRLV infection." (PMID 39860977, 2024). "In that study host genetic variation within the ovine gene TMEM154 was associated with reduced susceptibility to infection by OPPV." (PMID 36499292, 2022). "Our results here provide the most complete and novel investigation into the allele effects, gene action, and estimated impact on susceptibility to infection and total ewe productivity for all four common TMEM154 haplotypes present." (PMID 36499292, 2022). "In particular, the TMEM154 mutations for odds of infection have been shown to associate with reduced risk in American and European sheep and with improved control post-infection in some U.S. sheep." (PMID 34206933, 2021). "Significantly, an SNP linked to TMEM154, a locus controlling susceptibility to infection by Maedi-Visna, indicated that all three native hill breeds have a lower than average risk of infection to the lentivirus." (PMID 24489968, 2014). "In this study, we examined the relationship between SRLV control post-infection and variants in two genes, TMEM154 and CCR5, in four flocks containing 1403 SRLV-positive sheep." (PMID 24934128, 2014). "In conclusion, testing for association between control of SRLV post-infection and genotypes for TMEM154 and CCR5 variants suggests different approaches to further work in each case." (PMID 24934128, 2014). "Future work in flocks with more balanced allele frequencies is needed to confirm or refute TMEM154 association with control of SRLV post-infection." (PMID 24934128, 2014). "There has also been systematic genome-wide association for both odds of infection and proviral concentration, where many additional genomic regions were detected at similar or better association than the TMEM154 region." (PMID 23771240, 2013). "In conclusion, this GWAS found many additional genomic regions besides TMEM154 associated with odds of infection, and this was the first genome-wide study to provide regions associated with OvLV control as measured by proviral concentration." (PMID 23082221, 2012). "Two TMEM154 haplotypes encoding glutamate (E) at position 35 were associated with infection while a third haplotype with lysine (K) at position 35 was not." (PMID 22291605, 2012). "The ancestral TMEM154 allele encodes a 191 amino acid polypeptide with glutamate (E) at position 35 and is associated with infection susceptibility." (PMID 22291605, 2012).
infection (continued). "The odds of infection for ewes with one copy of a full-length TMEM154 E35 allele were 28 times greater than the odds for those without (p-value<0.0001, 95% CI 5–1,100)." (PMID 22291605, 2012). "Subsequent efforts were directed towards characterizing the genomic region of ovine TMEM154, discovering additional polymorphisms, and testing them for association with infection." (PMID 22291605, 2012). "This approach identified TMEM154 (nominal P = 9.2×10−7; empirical P = 0.13), provided 12 additional genomic regions associated with odds of infection, and provided 13 regions associated with control of infection (all nominal P<1×10−5)." (PMID 23082221, 2012). "In a combined analysis of nine cohorts with 2,705 sheep from Nebraska, Idaho, and Iowa, the relative risk of infection was 2.85 times greater for sheep with a full-length TMEM154 E35 allele (p-value<0.0001, 95% CI 2.36–3.43)." (PMID 22291605, 2012). "The ovine TMEM154 gene appears to be an OPPV susceptibility locus because the ancestral haplotype 3 was associated with infection." (PMID 22291605, 2012). "Thus, the selection based on TMEM154 polymorphisms represents a possible control tool for reducing the prevalence of infection in sheep." (PMID 40844279, 2025). "This animal was the only one in the study homozygous for the K allele at E35K TMEM154, raising the possibility that in addition to providing resistance to initial infection animals with this allele may be better able to control virus infection." (PMID 35144720, 2022). "In addition the one animal homozygous for the ‘K’ allele of the TMEM154 E35K SNP maintained very low viral loads in all assays and apparently cleared infection to below detectable limits at the final time point it was sampled." (PMID 35144720, 2022). "This is the first report of an association between TMEM154 diplotypes and SRLV proviral concentration, and the same desirable TMEM154 haplotypes associated with decreased proviral concentration in this flock were also associated with decreased SRLV odds of infection in a previous report." (PMID 24934128, 2014). "Prior to this study, it was unknown if TMEM154 associations with infection are influenced by SRLV genetic subgroups." (PMID 23895262, 2013). "These or other viral variants may influence probability of infection in animals of differing TMEM154 genotypes, and in the long term it is possible that viral variants might emerge to mitigate the partial resistance currently offered by these genotypes." (PMID 23771240, 2013). "Our results showed that variation in an ovine gene (TMEM154) was associated with infection." (PMID 22291605, 2012). "In addition, high infection pressure present in flocks analyzed (most of them were above 50% of infected animals) may have overwhelmed association with TMEM154." (PMID 33478070, 2021). "Considering the high genetic and antigenic variability of these viruses and the absence of an effective cure or vaccine, the genetic selection of resistant animals based on the TMEM154 gene represents an interesting opportunity to control the infection." (PMID 40844279, 2025). "This study presents an analysis of virus replication kinetics as it associates with TMEM154 and PARP14 gene expression in primary skin cells from three goats after in vitro infection with A5 as the known SRLV subtype." (PMID 41497468, 2025). "The observed relationship between expression of TMEM154 and PARP14 and cell permissiveness after SRLV infection suggest their involvement in the infection process, but their utility as susceptibility factors still needs to be verified." (PMID 41497468, 2025). "Our aim was to compare the four most prevalent TMEM154 haplotypes on the incidence of infection and ewe productivity during natural multiyear virus exposure." (PMID 36499292, 2022). "TMEM154 frequencies of raza Navarra, latxa Navarra, and churra breeds resembled those of resistant sheep, however, infection rate was high as determined by the combined strategy used." (PMID 33478070, 2021).
infection (continued). "Genetic variation in the ovine transmembrane 154 (TMEM154) gene associates with infection susceptibility, and distinct SRLV genetic subgroups infect sheep in association with their TMEM154 diplotypes." (PMID 25756342, 2015). "A separate region associated with odds of infection included SYTL3 (Synaptotagmin-Like 3) on ovine chromosome 8, and this region had the second largest odds ratio after TMEM154." (PMID 23082221, 2012). "Although variants in TMEM154 have consistent association with odds of infection, no variant in any gene has been associated with host control of OvLV post-infection in multiple animal sets." (PMID 24303974, 2014). "The purpose of this study was to carry out for the first time a survey to investigate the already known and de novo SNPs in TMEM154, CCR5, TLR9 and MYD88 target genes in some flocks reared in Italy, in order to identify variants that could confer resistance to SRLVs infection." (PMID 34372496, 2021). "The study aimed to analyse the expression of TMEM154 and PARP14 genes in primary skin cells of Carpathian goats following infection with the A5 subtype of SRLV." (PMID 41497468, 2025). "Additional barriers to infection that are independent of the TMEM154 locus may be required to prevent infection of sheep by subgroup 4 SRLVs." (PMID 25756342, 2015). "However, sheep with these TMEM154 haplotypes have not been examined for control of SRLV post-infection." (PMID 24934128, 2014). "A simple example would be association with other SRLV traits, and the literature so far has not addressed whether the current TMEM154 genetic marker test has a relationship with control of OvLV, in addition to odds of infection." (PMID 23771240, 2013). "Thus, these SRLVs may infect sheep that lack functional TMEM154, and may not be restricted by TMEM154 diplotypes in establishing infections." (PMID 25756342, 2015). "Markers in the first gene, TMEM154, had already been validated for SRLV odds of infection but had never been examined for any measure of control post-infection." (PMID 24934128, 2014).
cancer (1 paper, 2025). A tumor composed of atypical neoplastic, often pleomorphic cells that invade other tissues. "On the other hand, TMEM154 has not been previously associated with tumorigenesis or cancer treatment resistance." (PMID 40352330, 2025).
TMEM154 also shares sentences with these, for which no sentence is quoted: acute myeloid leukemia (1 paper); cervical adenocarcinoma (1); cervical cancer (1); cervical squamous cell carcinoma (1); glioma (1); mastitis (1); melanocytic neoplasm (1); melanoma (1); pneumonia (1).